EGF (epidermal growth factor)
Diseases named in the same sentence as EGF in open-access papers (continued):
Sharing a sentence is not in itself a finding about the gene and the disease.
tumor (continued). "In our previous studies, we have shown that crosstalk between MDA-MB-231-LN cells and LECs induce upregulation of EGF to promote MDA-MB-231-LN cell proliferation and LECs co-injected with MDA-MB-231-LN cells into nude mice enhanced tumor growth." (PMID 29898755, 2018). "This work also confirmed the involvement of the EGF and CSF-1 paracrine loop in tumor cell migratory streaming by using erlotinib to block the EGFR on tumor cells or by using CSF1R antibodies to block the CSF1R on macrophages." (PMID 29599778, 2018). "Human epidermal growth factor receptor 2 (HER2), located on chromosome 17q12-21, is a tyrosine kinase receptor in the epidermal growth factor (EGF) family and play a pivotal role in cell proliferation and tumor cell metastasis." (PMID 29381731, 2018). "Mounting research has shown that many tumours secrete a diversity of angiogenic factors (such as VEGFA, PDGFB, bFGF and EGF) to promote tumour angiogenesis." (PMID 30584257, 2018). "TAMs collaborate in angiogenesis through secretion of different substances among which stand out VEGF, epidermal growth factor (EGF), TGF-β, IL6 and matrix metalloproteinases (MMPs) that remodel the ECM in order to facilitate tumor growth." (PMID 30567306, 2018). "Subsequently, macrophages secrete factors, such as epidermal growth factor (EGF), platelet derived growth factors, and VEGF that promote cancer cell proliferation and angiogenesis of the tumor microenvironment." (PMID 29867776, 2018). "Under growth-promoting conditions in EGF, FGF enriched serum-free medium, miR-449a suppresses Ccnd1 and inhibits migration and invasion, suggestive of a tumour-suppressive effect." (PMID 29720725, 2018). "To demonstrate that tumor gene reprogramming promoted by EGF and PGE2-induced nuclear EGFR is critical for tumor progression, we have assessed cell proliferation by BrdU incorporation assay in NSCLC cells." (PMID 29599917, 2018). "Collectively, oncogenic G3BP1 serves as a signaling linkage molecule from upstream IL-6/EGF elicited stimulations to downstream STAT3 signaling, eventually contributing to promote tumor cell growth and metastasis in RCC." (PMID 29717134, 2018). "Various growth factors like epidermal growth factor (EGF), transforming growth factor-α (TGF-α) released within the tumor microenvironment activates UPR." (PMID 30159133, 2018). "In the current study, we did not observe marked nuclear localization of YB-1 after irradiation or EGF treatment, or following overexpression of KRAS(G12V) in tumor cells of different origins." (PMID 30126195, 2018). "Upon arrival, TAMs supply pro-migratory factors such as epidermal growth factor (EGF), promote proteolytic remodelling of the extracellular matrix, accelerate tumour motility and induce migration and invasion of tumour cells." (PMID 29065107, 2017). "We determined that EGF mRNA and protein expression levels were substantially upregulated in GBM tumor regions and edema zones." (PMID 29029486, 2017). "In a paracrine loop intra-tumoral macrophages secrete EGF, which binds to the EGFR on tumor cells, promoting their invasion." (PMID 28970798, 2017). "Bispecific EGF-IGF-LDP-AE at 0.2 mg/kg and 0.4 mg/kg yielded tumor growth inhibition of 69.7% and 80.5%, respectively, whereas the lidamycin-treated group at maximum tolerated dosage (0.05 mg/kg) only showed inhibition rate of 59.4% (p < 0.01)." (PMID 28460483, 2017). "Among the PTEN-regulated chemo- and cytokines we verified differential expression of CSF2 (also known as GM-CSF), EGF and VEGFA by tumor cells." (PMID 28008153, 2017). "The expression of epidermal growth factor, CXCL9, CCL25, and matrix metalloproteinases‐9 by HCC cells differed between primary tumor sites and metastatic regions." (PMID 28205428, 2017). "EGF-IGF-LDP-AE at 0.2 mg/kg and 0.4 mg/kg both yielded significant tumor growth inhibition (69.7% and 80.5%, respectively; p < 0.01 compared with the PBS-treated group, p < 0.05 between two different dosages)." (PMID 28460483, 2017).
tumor (continued). "These cells can enhance tumor angiogenesis, immunosuppression, tumor cell invasion and metastasis via the production of different cytokines and chemokines such as VEGF-A, CCL17/CCL22, and EGF." (PMID 28848446, 2017). "It has been reported that the levels of TAM-derived tumor growth factor-β1 (TGF-β1), epidermal growth factor (EGF), chemokine [C-C motif] ligand 18 (CCL18), interleukin (IL)-18, IL-1β, and IL-8 are correlated with tumor progression." (PMID 28143526, 2017). "Tyrosine kinase receptors, including those for EGF, TGF-α and PDGF-A, also interact with ECM receptors to increase tumor progression." (PMID 28883992, 2017). "It is also established that the L3.6pl cell line produces relatively high levels of epidermal growth factor (EGF) and that in tumor models signaling through the EGF receptor potentiates endothelial cell survival." (PMID 28916756, 2017). "Labelling of the natural ligand, EGF, with 68Ga31 or 18F 32 enabled specific imaging of EGFR-expressing xenografts with tumour-to-blood ratios in the range of 2–5." (PMID 28729680, 2017). "In a combined human and animal ex vivo study, labeling quantum dots (QDs) with EGF and anti-EGFR antibodies visualized individual tumor cells with confocal imaging reaching a TNR as high as 1000, even for LGGs." (PMID 27878374, 2017). "TGF-β, FGF, epidermal growth factor (EGF), and HGF induce EMT, tumor proliferation and survival, and resistance to anti-cancer agents." (PMID 27965469, 2017). "In the tumor microenvironment, growth factors and cytokines, such as hepatocyte growth factor (HGF) and epidermal growth factor (EGF), are frequently secreted from tumor cells and/or tumor-associated stromal and inflammatory cells." (PMID 28587113, 2017). "Intravital imaging of flank tumor xenografts after EGF-Rh injection revealed co-localization of EGFR-GFP and EGF-Rh in perinuclear vesicles and clusters located proximally or overlapping with the plasma membrane." (PMID 29268862, 2017). "Imaging of EGF-Rh and EGFR-GFP fluorescence on flank tumor sections demonstrated the presence of vesicles containing both ligand and receptor in a large population of cells." (PMID 29268862, 2017). "Herein, we demonstrate that coactivation of EGF and EGFR drives tumor metastasis in a matrix metalloproteinase-9 (MMP-9)–dependent manner." (PMID 29029486, 2017). "TAMs, which in time polarize toward M2 phenotype with poor antigen-presenting capability and immunosuppressive activity by releasing immunosuppressive factors (IL-10, TGF-β, EGF, VEGF, MMPs), are regarded to be pro-tumor for many cells." (PMID 28343267, 2017). "Considerably, analysis of SM-related modules revealed multiple tumour-promoting pathways such as PI3K-Akt, PLD, and EGF/EGFR SPs which were commonly found in the NSCLC group." (PMID 29062084, 2017). "Cetuximab, as an EGFR inhibitor, can block the combination between EGFR and its ligands competitively, such as epidermal growth factor (EGF), resulting in inhibition of growth, invasion, and metastasis of tumor cells." (PMID 29390545, 2017). "It has been shown that GMI suppressed the EGF-mediated migration and invasion via blockage of PI3K/Akt pathway and the TNF-α-induced tumor invasion and inflammation through inhibition of NF-κB/MMP-9 pathway in human alveolar epithelial A549 cells." (PMID 29050290, 2017). "Upregulation of epidermal growth factor (EGF) and its receptor (EGFR) has been demonstrated to correlate with enhanced PC tumor aggressiveness and shorter survival periods." (PMID 28383487, 2017). "We obtained similar results in vitro, in which newly activated LC3 coincided with dysfunctional mitochondria and DNA damage in EGF-injected tumors, suggesting that the EGF–EGFR network also induced cell death via Ref-1 activation in a xenograft tumor model." (PMID 27935858, 2017). "Mechanistically, tumour cells secrete CSF1, which stimulates macrophages to produce EGF that in turn activates migration of the tumour cells." (PMID 29065107, 2017).
tumor (continued). "Lastly, the antitumor effect of PDBD was supported by the changes in colony size when two tumor promoters, tetradecanoyl phorbol acetate (TPA) and epidermal growth factor (EGF), were injected into the CRC cells." (PMID 28225083, 2017). "CAFs were also shown to modulate the tumor microenvironment by the expression of VEGF-A and EGF and thus contribute to angiogenesis." (PMID 28402937, 2017). "In summary, bakuchiol inhibits EGF-induced neoplastic transformation of HaCaT and JB6 P+ cells and also reduces tumor growth in an A431 mouse xenograft model." (PMID 26910280, 2016). "The GHRH antagonist MZ-J-7-114 was shown to block the activities of VEGF and downregulate the expression of epidermal growth factor (EGF) and VEGF receptors, thereby effectively abolishing angiogenesis and tumor growth." (PMID 27774107, 2016). "Among these factors are the epidermal growth factor (EGF) and its receptor (EGFR) and the vascular endothelial growth factor (VEGF) and its receptor (VEGFR), which constitute key elements in tumor growth and dissemination." (PMID 27806094, 2016). "Tumor cells undergoing EMT express specific factors, including cytokines and chemokines, such as TGF-β, FGF, and EGF." (PMID 27050434, 2016). "On the other hand, tumor cells can produce some of the same cytokines, angiogenic, and growth factors released by MSC such as IL-8, PDGF, EGF, TGF-β, IL-1β, and TNF-α, which can trigger MSC migration." (PMID 27834810, 2016). "The transcription of the MMPs is induced by inflammatory cytokines, such as IL-1, IL-6, TNF-α, and growth factors such as EGF, HGF, and TGF-β, giving them a preponderant role in the chronic inflammation which is present in the tumour microenvironment." (PMID 26913068, 2016). "Using 288 single cells, we constructed high‐resolution phylogenies of EGF‐driven and PDGF‐driven GBMs, modeling transcriptional kinetics during tumor evolution." (PMID 27888226, 2016). "Cannabidiol inhibits the EGF/EGFR pathway and alters cytokine production in tumor cells, leading to a reduction in the numbers of total and M2 macrophages at the primary and secondary tumor sites." (PMID 27683110, 2016). "The genetic and epigenetic alterations acquired by carcinoma cells during primary tumor formation are likely to increase their responsiveness to various contextual signals such as TGF-β, TNF-α, IL-6 and EGF." (PMID 26909601, 2016). "Our findings, demonstrating that reduced expression of MCT1 dramatically limits EGF- and HGF-induced cell motility, are somewhat expected given the known role of MCT1 transporter activity in tumor progression." (PMID 27127175, 2016). "MET‐pos‐NS were kept in a standard EGF/bFGF medium, supplied with HGF to better mimick the brain (tumor) microenvironment." (PMID 27138567, 2016). "TNBC tumor cell lines were pre-treated with the Src kinase-specific inhibitor AZM475271 and then stimulated with either IL-17E or EGF." (PMID 27462789, 2016). "Instead, secondary events, such as inflammation-induced signaling activation of the epidermal growth factor (EGFR) or induction of Sox9 expression, are required for tumor formation." (PMID 26697077, 2016). "Tumor cells secrete CSF-1 that promotes TAM production of EGF, and TAM-derived EGF stimulates tumor cell CSF-1 secretion." (PMID 26980947, 2016). "This is due to the secretion of the epidermal growth factor (EGF), platelet-derived growth factor (PDGF), TGF-β, IL-6, IL-1, and tumor necrosis factor (TNF)-α of TAMs, which creates a favorable milieu for tumor growth." (PMID 27044404, 2016). "In vitro, the joint activity of the three factors, applied together as TME Stimulation (estrogen+TNFα+EGF), was much more potent than of each factor alone, leading to tumor cell remodeling towards an EMT-like phenotype and increased tumor cell scattering." (PMID 27835603, 2016).
tumor (continued). "Increased cell proliferation, tumor volume and weight with the SLC3A2-NRG1 fusion were significantly eliminated when a SLC3A2-NRG1Δ EGF truncated form was used in the same cancer cells." (PMID 27626312, 2016). "The tumor stimulating activities of the eight analyzed growth factors, including VEGF, EGF, PDGF-BB, NGF-β, SCF, TNF-α, FGF-β, and TGF-β, have been demonstrated in many studies." (PMID 27151407, 2016). "In the three cell lines most sensitive to EGF (LN229, LN308, and LN428), CD151 knockdown led to a 2- to 7-fold decrease in the number of tumor cells invading through the Matrigel after EGF stimulation." (PMID 26377974, 2015). "Furthermore decrease of apoptotic cells after HGF addition to canertinib 2 uM in Res-259 cells and after EGF addition to sorafenib 1 uM in Res-196 cells, could also be exceeded by crizotinib or canertinib respectively (61,5% and 36.9% more apoptotic tumor cells)." (PMID 25799134, 2015). "ELISA analysis revealed increased expression of STAT3-activating cytokines such as EGF, OSM and IL-6 in lungs harbouring KrasG12D-driven tumours compared with healthy control lungs." (PMID 25734337, 2015). "To clarify the mechanism involved in the regulation of tumor metastasis by EGF-induced COX-2, we examined changes in EMT markers in cells treated with EGF or PGE2." (PMID 25595899, 2015). "Thus, our results further reinforce the importance of extending the mutation screening tests to the less frequent hotspot mutations such as codon 146 or 61, which could determine the EGF-response going from signal transduction to the global acetylome of tumor cells." (PMID 26110767, 2015). "EGF and HGF showed to be effective rescue inducing growth factors in these tumor escape mechanisms acting via their RTKs resulting in increased cell survival and downstream signaling." (PMID 25799134, 2015). "In addition, we studied whether PTX3 contributed to EGF-induced tumor invasion." (PMID 25797258, 2015). "It has been demonstratedthat tumours overexpressing both EGFR and c-Src have increased EGF-mediated DNAsynthesis, soft agar growth, increased phosphorylation of receptor-binding proteins(Shc, PLC-γ) and increased tumourigenesis in nude mice." (PMID 25658745, 2015). "EGF, HGF and FGF, which are normally expressed in brain (tumor) tissue, showed to be effective rescue inducing growth factors resulting in increased cell survival especially during treatment with dasatinib (complete rescue) or sorafenib (partial rescue)." (PMID 25799134, 2015). "We have shown that endothelial cells secrete IL-6, CXCL8, and EGF that induce phosphorylation of STAT3, AKT, and ERK in tumor cells, and that these phosphorylation events enhance tumor cell survival and migration." (PMID 26287605, 2015). "The autocrine production of EGF-induced PTX3 altered the expression of metastatic molecules, such as increasing fibronectin and MMP-9, resulting in enhanced tumor metastasis." (PMID 25797258, 2015). "As a result, EGCG drastically reduced epidermal growth factor-induced EGFR phosphorylation, which plays the crucial role in tumor cell growth and survival." (PMID 26135316, 2015). "All cells were grown in ‘base’ medium, and the non-tumor lines MCF10A and MCF12A were also cultured ‘complete’ medium, as MCF10A cells required EGF to proliferate." (PMID 26148352, 2015). "To better understand the relationship between tumour microenvironment parameters and cell invasion, we studied the effects of HGF, EGF, IGF, netrin, PDGF-B, TNF-α, bFGF, IL-6, NGF, TGF-β and PlGF-1 in the 3D environment." (PMID 26486848, 2015). "Addition of HGF or EGF phosphorylated MET or EGFR, respectively, and demonstrated phosphorylation of Akt and ERK1/2 as well as increased tumor cell viability." (PMID 26496080, 2015). "Phosphorylated and total RSK protein levels were increased in a time-dependent manner with EGF or TPA treatment, suggesting that the tumor promoters EGF and TPA activated the ERKs/RSK signaling pathway." (PMID 26083344, 2015).
tumor (continued). "Cancer cells produce numerous angiogenic factors, including VEGF, FGF, EGF, PDGF etc, which play a pivotal role in the development of tumor angiogenesis by stimulating endothelial cell proliferation, migration, and capillary tube formation." (PMID 25789853, 2015). "Intriguingly, we found a correlation between EGF treatment and miR-622 reduction under hypoxia, which led to an elevated HIF-1α level and promoted tumor cell invasion." (PMID 26528854, 2015). "Although M2 macrophages were known to promote tumor metastasis by secreting TGF-β, EGF, FGF and VEGF, our study showed that M2 macrophages did not exert a significant pro-metastatic effect." (PMID 26474279, 2015). "Important tumor related growth factors which are normally expressed in the developing brain binding RTKs include VEGF, EGF, HGF, FGF and PDGF." (PMID 25799134, 2015). "In serum-free medium containing EGF and basic-FGF these cells grow as tumor spheroids expressing stem cell markers such as CD133." (PMID 26219257, 2015). "EGF blockade also interferes with VEGF production by tumour cells, suggesting a complementary anti-tumour effect during combination therapies of cetuximab and bevacizumab." (PMID 26517691, 2015). "Small interfering RNA knockdown of SNX1 levels in tumor cell lines resulted in increased proliferation, decreased apoptosis, decreased anoikis, increased EGFR phosphorylation after EGF stimulation, and increased downstream signaling." (PMID 24700353, 2014). "Many signals received from the tumor microenvironment can initiate EMT including TGFβ, hypoxia-inducible factor (HIF)-1α, EGF, WNTs, and Notch." (PMID 25566498, 2014). "There is mutual antagonism between 1α,25(OH)2D3 and epidermal growth factor (EGF), a potent mitogen, in primary colon epithelial cells and in established colon (Caco-2) and breast (T47D) tumor cell lines." (PMID 24600406, 2014). "The average response to EGF across all cell lines in a 2D monolayer was a 2.67 fold increase in EGFR phosphorylation, while there was only a 1.5 fold increase in tumor spheroid cell lines." (PMID 24638075, 2014). "For this reason, real ligands, such as epidermal growth factor (EGF) and fibroblastic growth factor (FGF), can be studied for tumor targeting." (PMID 24549268, 2014). "When monolayer or spheroid cultures were stimulated with EGF or HGF, all of the tumor cell lines, cultured as 3D spheroids, were less responsive to growth factor stimulation (phosphorylation of EGFR and cMET, respectively) than cells grown as 2D monolayers." (PMID 24638075, 2014). "CRIPTO-1 is a member of the epidermal growth factor-CRIPTO-1/FRL-1/Cryptic (EGF/CFC) family, abundantly expressed in embryonic stem cells and tumor cells." (PMID 25165718, 2014). "In the present study, melanospheres were derived directly from tumor specimens (PDM, patient-derived melanospheres) and maintained in the bFGF(+)EGF(+) serum-free medium." (PMID 24733089, 2014). "Together, these findings substantiate a role of EGF-mediated signaling not only in EMT and proliferative signaling itself but also in the cross-talk between tumor cells and the microenvironment." (PMID 25566498, 2014). "Based on the effect of tumor inhibition obtained from the MTT assay, expression of the growth factors EGF, HGF, and VEGF related to tumor growth through real-time quantitative PCR, Western blotting, and ELISA was decreased." (PMID 25068796, 2014). "In contrast, expression of both epidermal growth factor (EGF) and platelet growth factor (PGF) was significantly reduced in PEMs from SEMA7A KD tumor bearing mice." (PMID 24550834, 2014). "In recent years, we and others described a novel NIR bio-imaging approach for CRC models using EGF-NIR which binds and visualize the heterogeneous expression of EGFR in CRC preclinical human tumor cell lines and clinical tissues." (PMID 23857061, 2013). "Epidermal growth factor (EGF) plays a critical role in malignant transformation of hepatocytes and tumor progression." (PMID 23419149, 2013).